CNGB1 (cyclic nucleotide gated channel subunit beta 1)
Diseases named in the same sentence as CNGB1 in open-access papers:
CNGB1 is named in the same sentence as 31 diseases in open-access papers, as found by Europe PMC text mining. Sharing a sentence is not in itself a finding about the gene and the disease. The quoted sentences say what the papers report.
retinal degeneration (23 papers, 2008 to 2026). Degeneration of the retina. "Recently, olfactory dysfunction in association with retinal degeneration has been described in CNGB1-related disease and later coined RP-olfactory dysfunction syndrome." (PMID 37107588, 2023). "The aim of this study was to report the molecular spectrum along with the ocular and olfactory phenotypes of a multiethnic cohort with genetically confirmed CNGB1-associated retinal degeneration." (PMID 37107588, 2023). "Even though CNGB1-related retinal degeneration is well described, only three studies have associated CNGB1 variants with both RP and olfactory dysfunction." (PMID 37107588, 2023). "Knockout mutation of Nrl leads to the loss of rod cells while mutations in Gnb3, Cnga1, and Cngb1 have been shown to lead to night blindness in humans and retinal degeneration in chickens." (PMID 36576130, 2022). "Recently, we identified a spontaneous mutation in canine Cngb1 in dogs with recessively inherited progressive retinal degeneration." (PMID 29202463, 2018). "The CNGB1-deficient mice developed retinal degeneration that resembles human RP, progressing from the rod degeneration to a complete loss of rod function and secondary degeneration of the cones." (PMID 24015210, 2013). "CNGB1 is important for the photoreceptor cell function its defects have been previously associated with retinal degeneration in both human and mouse." (PMID 24015210, 2013). "The approach identified genes that cause retinal degeneration (CNGB1, SEMA4A, RRG4) or developmental changes (SOX2) when mutated." (PMID 18334927, 2008). "Therefore, although we lack functional data due to limited access to retinal tissues from the affected dogs, it is likely that the mutation abrogates CNGB1 functions and causes retinal degeneration in Papillons and Phalènes." (PMID 24015210, 2013). "The early onset of loss of rod function in the CNGB1-fs26 mutant dog, coupled with a slow retinal degeneration that we have observed in our colony dogs, seems to accurately parallel the described disease course in human patients as well as the comparable mouse model (CNGB1X-26)." (PMID 23977260, 2013). "The defective CNGB1 has been implicated as a cause of retinal degeneration in human and mouse." (PMID 24015210, 2013). "The link between calcium influx and photoreceptor death in Pde6 mutants has been confirmed with genetic studies as Cngb1−/− knockout incorporated into Pde6g−/− and rd10 background delayed retinal degeneration in these mice." (PMID 40631959, 2025). "Surprisingly, while BAPTA-AM led to photoreceptor cell death in rd1*Cngb1−/− retina, perhaps due to Ca2+ depletion, NCX inhibition in the rd1*Cngb1−/− situation attenuated retinal degeneration, indicating that NCX is in forward mode when CNGC activity is low." (PMID 38303059, 2024). "To account for this slower retinal degeneration phenotype in the double-mutant retina, we performed D-cis-diltiazem and Olaparib treatments on organotypic retinal tissue cultures derived from rd1*Cngb1−/− animals at P7 and cultured until P17." (PMID 35327647, 2022). "Thereby, they used Cngb1−/− mice to investigate the extent of microglia activation in retinal degeneration as well as gene expressions of Cngb1−/− and respective wildtype animals." (PMID 36291747, 2022). "Knockout studies on the Cngb1−/− x rd1 and Cngb1−/− x rd10 double-mutants suggested an important role for CNGC in retinal degeneration." (PMID 33864120, 2021). "Here, we used Cngb1−/− mice, which represent a slow degenerative mouse model of RP, to investigate the extent of microglia activation in retinal degeneration." (PMID 29354133, 2017). "At 28 days after birth (P28), minor (~15%) but significant retina degeneration was observed in Cngb1−/− mice and more than 1,000 genes were dysregulated (>1.5-fold dysregulated, p < 0.05, STab.1) as seen from Affymetrix gene chip arrays." (PMID 29354133, 2017).
retinal degeneration (continued). "Our data suggest that Cngb1−/− microglia are potentially an early driving force, which substantially contributes to the retinal degeneration and long-term visual impairments found in RP." (PMID 29354133, 2017). "We identified a total of nine causal mutations, including six novel variants in RPE65, LCA5, USH2A, CNGB1, FAM161A, CERKL and GUCY2D as the underlying cause of inherited retinal degenerations in 13 of 26 pedigrees." (PMID 26352687, 2015). "PRKG1 deficiency does not prevent retinal degeneration in Pde6g-/- mice but does so in Cngb1-/- mice, even though cell death in both cases is caused by cGMP elevation." (PMID 38350962, 2024). "Additionally, we thoroughly characterized the retinal and olfactory phenotypes of 15 CNGB1-related retinal degeneration patients from ten different families and found that only 4 patients had a preserved sense of smell." (PMID 37107588, 2023). "Subretinal delivery of normal gene using AAV2.1 (under the control of rhodopsin promoter) in Cngb1-null mice of autosomal recessive retinitis pigmentosa restored retinal morphology, CNGB1 channel expression, rod driven light responses in the retina, and delayed retinal degeneration." (PMID 32967234, 2020). "Consistent with the phenotype observed in the cohort of patients analyzed in this study, the RPE65, LCA5, USH2A, CNGB1, FAM161A, CERKL and GUCY2D genes consisting mutations in 13 of the 26 pedigrees have been implicated in causing recessive non-syndromic retinal degeneration." (PMID 26352687, 2015). "In addition, the mutation was studied in 121 dogs from 44 other breeds affected with PRA or retinal degeneration, but none of these affected dogs had the CNGB1 mutation." (PMID 24015210, 2013). "This study highlights the critical role that CNG channels play in some forms of retinal degeneration, consistent with the recent discovery that a CNG channel knockout (CNGB1−/−) can rescue rod photoreceptors in rd1 mice." (PMID 23805033, 2013). "An early onset of nyctalopia in the absence of marked retinal degeneration is explained by CNGB1 subunits’ crucial role in rod photoreceptor activity." (PMID 37107588, 2023). "A mouse model of CNGB1‐retinopathy lacking exon 26 (Cngb1‐X26) is characterized by a slow progressive retinal degeneration with cell apoptosis and retinal gliosis." (PMID 33847019, 2021). "Finally, dual inhibition of CNG channel activity and PKG signaling may achieve the best effect, as the knockout of Prkg1 was found to slow retinal degeneration in Cngb1−/− but not in Pde6g−/− mouse models." (PMID 40631959, 2025).
retinitis pigmentosa (14 papers, 2010 to 2026). Retinitis pigmentosa (RP) is an inherited retinal dystrophy leading to progressive loss of the photoreceptors and retinal pigment epithelium and resulting in blindness usually after several decades. "Mutations in Cngb1 cause retinitis pigmentosa (RP45), and β‐subunit knockout mice are studied as models of this disease." (PMID 41292168, 2026). "CNGB1 variants are associated with retinitis pigmentosa, a degenerative eye disease that affects photoreceptor function." (PMID 41442065, 2025). "Disease‐causing sequence variants in CNGB1 lead to autosomal recessive rod‐cone dystrophy/retinitis pigmentosa (RP)." (PMID 33847019, 2021). "In this study, we found novel heterozygous nonsense mutations of CNGB1 gene segregating with retinitis pigmentosa phenotype in the proband, with autosomal recessive (compound heterozygosity) inheritance." (PMID 29179439, 2017). "In conclusion, here, we report a Chinese patient who presented with retinitis pigmentosa, with novel mutations in the CNGB1 gene." (PMID 29179439, 2017). "Our findings expand the mutational spectra of CNGB1 and are valuable in the mutation-based pre- and post-natal screening and genetic diagnosis for retinitis pigmentosa." (PMID 29179439, 2017). "Previously, we have shown that genetic ablation of the Cngb1 gene encoding the B subunit of the rod CNG channel delays the fast progressing degeneration in the rd1 mutant mouse model of retinitis pigmentosa." (PMID 27270916, 2016). "This indicates that CNGB1 mutations may represent a genetic basis for the comorbidity of retinitis pigmentosa and olfactory dysfunction, providing a valuable foundation for the diagnosis of similar disorders." (PMID 39769024, 2024). "Bi-allelic pathogenic variants of CNGB1 are known to cause retinitis pigmentosa." (PMID 34064005, 2021). "Germline mutations of CNGB1 is associated with retinitis pigmentosa." (PMID 29179439, 2017). "Here, we assessed this follow-up in a model of Retinitis Pigmentosa (RP) lacking the gene encoding the rod nucleotide-gated channel subunit CNGB1." (PMID 24927180, 2014).
autosomal recessive retinitis pigmentosa (6 papers, 2008 to 2023). Autosomal recessive retinitis pigmentosa (RP) is an autosomally recessive inherited retinal dystrophy leading to progressive loss of the photoreceptors and retinal pigment epithelium and resulting in blindness usually after several decades. "CNGB1 gene mutations are a well-known cause of autosomal recessive retinitis pigmentosa (RP), which was recently associated with olfactory dysfunction." (PMID 37107588, 2023). "Pathogenic variants in CNGB1 are responsible for 4% of autosomal recessive retinitis pigmentosa (RP)." (PMID 35743231, 2022). "Pathogenic variants in CNGB1 account for up to 4% of autosomal recessive retinitis pigmentosa (RP) cases (RP45 #613767)." (PMID 35743231, 2022). "Patients #2–4 were recently characterized clinically in association with mutations or VUS in the gene CNGB1 associated with autosomal recessive retinitis pigmentosa (arRP)." (PMID 34209753, 2021). "Homozygous mutations in CNGA1 and CNGB1 result in autosomal recessive retinitis pigmentosa (RP), a genetically heterogeneous group of retinal degenerative diseases with variable clinical phenotype, characterized by the degeneration of RPE and photoreceptors." (PMID 32967234, 2020). "Germline mutations in CNGB1 genes is associated with autosomal recessive retinitis pigmentosa (arRP) very rare." (PMID 29179439, 2017). "CNGB1 is mutated in autosomal recessive retinitis pigmentosa (ARRP, OMIM 600724) and is expressed in the brain (UniGene Hs.147062), where it was found regulated in ischemia." (PMID 18334927, 2008).
night blindness (5 papers, 2018 to 2023). Inability to see clearly in dim light. "In summary, we show that patients with mutations in CNGB1 have night blindness from childhood, with a slow loss of photoreceptors." (PMID 29202463, 2018). "Clinically significant CNGB1 variants are a known cause of autosomal recessive RP (MIM#613767), characterized by the onset of night blindness during childhood but a relatively preserved visual acuity until the late stages of the disease." (PMID 37107588, 2023). "Overall, our study is consistent with the previous findings that suggest that CNGB1‐related RP has a good prognosis for central vision despite the early onset of night blindness." (PMID 33847019, 2021). "According to our case with a CNGB1 and GNAT1 mutation, mild visual symptoms, including good BCVAs, emmetropic to mild myopia, and night blindness, were documented, which were similar to prior clinical findings." (PMID 34064005, 2021).
retinal dystrophies (4 papers, 2013 to 2022). "On the other hand, other photoreceptor-specific proteins containing glutamic acid-rich domains (i.e., CNGB1) have been associated with retinal dystrophies, even though their interactions have been better defined." (PMID 35806195, 2022).
retinoblastoma (3 papers, 2021 to 2024). A malignant tumor that originates in the nuclear layer of the retina. "We have successfully identified a few gene signature (CLUL1, CNGB1, ROM1 and RDH12) to predict the risk of invasion in retinoblastoma and therefore, in this study, we investigated the profiles of invasive risk panel between subtypes." (PMID 37777551, 2023). "It has been reported that CLUL1, CNGB1, ROM1, LRRC39, and RDH12 genes in different retinoblastoma subtypes are involved in the progression and development of the disease, which can be useful as biomarkers (M.)." (PMID 34646884, 2021). "Interestingly, the retinoblastoma invasion markers (CLUL1, CNGB1, ROM1 and RDH12) were predominantly higher in subtype 1b, suggesting subtype 1b retinoblastoma prone to be more invasive as compared with other subtypes." (PMID 37777551, 2023).
achromatopsia (1 paper, 2023). Achromatopsia (ACHM) is a rare autosomal recessive retinal disorder characterized by color blindness, nystagmus, photophobia, and severely reduced visual acuity due to the absence or impairment of cone function. "Four of the CNG channel genes are linked to inherited retinal disorders (IRD): mutations in CNGA1 and CNGB1 are known to cause retinitis pigmentosa (RP) and mutations in CNGA3 and CNGB3 cause achromatopsia (ACHM)." (PMID 36830806, 2023).
Autoimmunity (1 paper, 2017). The occurrence of an immune reaction against the organism's own cells or tissues. "The small CD45hi CD11b− cell population found in Cngb1-wt and Cngb1-ko retinas presumably represents circulating retina-specific T cells, which have been reported to protect against spontaneous organ-specific autoimmunity." (PMID 29354133, 2017).
bladder cancer (1 paper, 2021). "Recently, a clinically aggressive variant of bladder cancer, sarcomatoid carcinoma, was shown to carry frequent mutations of CNGB1." (PMID 34359804, 2021).
breast carcinoma (1 paper, 2022). "Thus, the biological significance of DLX6 and CNGB1 gene mutations in lung adenocarcinoma patients with breast cancer still needs to be further investigated." (PMID 35668376, 2022). "Furthermore, the mutations of TRIM73, DLX6 and CNGB1 and high expression of FGF10 and VEGFA might play an important role in the development of lung adenocarcinoma in breast cancer patients." (PMID 35668376, 2022). "Thus, TRIM73, DLX6 and CNGB1 may be relatively characteristic genes in pulmonary adenocarcinoma patients with previous breast cancer." (PMID 35668376, 2022).
glaucoma (1 paper, 2021). Increased pressure in the eyeball due to obstruction of the outflow of aqueous humor. "These 13 glaucoma-associated genes can be divided into three functional groups: phototransduction-related genes (GNGT1, OPN1SW, PDE6A, PDC, CRX, CNGB1, GUCY2F), glutamate receptor (GR) genes (GRIN2B, GRIK3, GRIK4), and 5-hydroxytryptamine receptor (HTR) genes (HTR1A, HTR1E, HTR7)." (PMID 33874942, 2021).
lung carcinoma (1 paper, 2021). "The level of CEACAM5 (P < 0.001), CNGB1 (P < 0.001), CSTL1 (P < 0.001), RASAL1 (P < 0.001), SLC4A3 (P < 0.001) expression were also increased in lung tissues of patients with lung cancer coexisting COPD compared to controls." (PMID 33791201, 2021). "The level of CEACAM5 (P < 0.001), CNGB1 (P = 0.001), CSTL1 (P = 0.009), RASAL1 (P < 0.001) expression were higher in lung tissues of patients with lung cancer alone than controls." (PMID 33791201, 2021). "The role of RASAL1 in COPD and lung cancer has not been investigated, which may relate to matrix metalloproteases involving in inflammation and cancer invasion and metastasis CNGB1 (cyclic nucleotide gated channel subunit beta 1) encodes a cyclic nucleotide gated channel." (PMID 33791201, 2021). "In addition, the level of CEACAM5 (P = 0.030), CNGB1 (P = 0.042), CSTL1 (P = 0.046), RASAL1 (P = 0.039), SLC4A3 (P = 0.035) expression were higher in patients with lung cancer coexisting COPD than that in patients with lung cancer alone." (PMID 33791201, 2021).
uveitis (1 paper, 2024). An inflammatory process affecting a part of or the entire uvea. "Since CD44 is expressed in reactive microglia cells from Cngb1-knockout retinas and from retinas following endotoxin induced uveitis, we analyzed retinal sections and retinal flatmounts from 12-week-old ST/ST mice that were co-immunostained for IBA1 to visualize microglia/macrophages and CD44." (PMID 39095775, 2024).
tumours (3 papers, 2020 to 2021). "Similarly, in primary tumours these genes showed significant downregulation (3–4-fold), together with other genes associated with light perception and phototransduction, such as Cngb1, Nrl (6-fold) or Bhlhe40." (PMID 32581213, 2020). "We further evaluated CNGB1 expression using a tissue microarray comprising tumours from our own cohort of 99 patients with MIBC (Validation cohort 2)." (PMID 34359804, 2021). "Interestingly, after analyzing the CNGB1 expression landscape across different types of normal-tumor tissue pairs, we found that it was only significantly over-expressed in Head and Neck Squamous Carcinoma (HNSC)." (PMID 34093800, 2021). "Additionally, we identified Olfactory transduction (CNGB1) as a novel enriched signaling pathway from the subset of genes exclusively expressed in TCGA-ESCC patient tumor tissues." (PMID 34093800, 2021).
cancer (2 papers, 2021). A tumor composed of atypical neoplastic, often pleomorphic cells that invade other tissues. "Kaplan-Meier analysis of a further cohort of MIBC patients (validation cohort 2, n = 99) demonstrated that a high level of CNGB1 expression associated with shorter cancer specific survival (p < 0.001)." (PMID 34359804, 2021).
CNGB1 also shares sentences with these, for which no sentence is quoted: Retinopathy (2 papers); B cell lymphoma (1); Blindness (1); choroideremia (1); clear cell renal cell carcinoma (1); dyslexia (1); Leber congenital amaurosis (1); lung adenocarcinoma (1); malaria (1); myopia (1); psychiatric disorder (1); Recessive Retinitis Pigmentosa (1); Retinal atrophy (1); rod-cone degeneration (1); sarcomatoid carcinoma (1); schizophrenia (1).